IMPDH1 (inosine monophosphate dehydrogenase 1)
Description:
Catalyzes the conversion of inosine 5'-phosphate (IMP) to xanthosine 5'-phosphate (XMP), the first committed and rate-limiting step in the de novo synthesis of guanine nucleotides, and therefore plays an important role in the regulation of cell growth. Could also have a single-stranded nucleic acid-binding activity and could play a role in RNA and/or DNA metabolism. It may also have a role in the development of malignancy and the growth progression of some tumors.
Synonyms: IMPD1; sWSS2608; LCA11; IMPD; IMPDH-I; RP10
Tractability: Small molecule: an approved drug acts on it; a structure with a bound ligand is known; a high-quality ligand is known; it has a binding pocket of medium quality; it belongs to a druggable protein family. Antibody: its Gene Ontology location is reachable by antibodies, with high confidence. PROTAC: ubiquitination databases record sites on it; its protein half-life has been measured; a small molecule that binds it is known.
Target class: Enzyme; Oxidoreductase
Chemical probes: PD081263, PD082638, PD084376, PD084805
Safety:
Unwanted effects reported when the protein is acted on. In parentheses: how it was acted on, where the effect was seen, and who reports it.
acute rejection after kidney transplantation (source: ClinPGx)
gastrointestinal intolerance (source: ClinPGx)
leukopenia (source: ClinPGx)
Gene: Protein-coding gene on chromosome 7 (128,392,277 to 128,410,009, reverse strand). Ensembl gene ENSG00000106348.
Subcellular location: Cytoplasm; Nucleus
Subcellular location (Human Protein Atlas): Cytosol; Rods & Rings
Pathways (Reactome):
Disease: Potential therapeutics for SARS
Drug ADME: Azathioprine ADME
Immune System: Neutrophil degranulation
Metabolism: Purine ribonucleoside monophosphate biosynthesis
Gene Ontology:
Molecular function: DNA binding; nucleic acid binding; IMP dehydrogenase activity; catalytic activity; metal ion binding; nucleotide binding; oxidoreductase activity
Biological process: GTP biosynthetic process; 'de novo' XMP biosynthetic process; GMP biosynthetic process; purine nucleotide biosynthetic process
Cellular component: cytoplasm; cytosol; nucleus; azurophil granule lumen; extracellular region; ficolin-1-rich granule lumen; secretory granule lumen
Genetic constraint (gnomAD): Loss-of-function variants: 41 observed, 69.69 expected, observed/expected ratio (o/e) 0.59, 90% interval 0.46 to 0.76. The upper end of that interval is the gene's LOEUF score, 0.76, which puts it in group 3 of 6, group 1 being the genes least tolerant of losing a copy. Missense variants: 645 observed, 795.1 expected, observed/expected ratio (o/e) 0.81, 90% interval 0.76 to 0.87. Synonymous variants: 318 observed, 317.29 expected, observed/expected ratio (o/e) 1, 90% interval 0.91 to 1.1.
Gene-disease validity (ClinGen):
ClinGen rates the evidence that IMPDH1 causes each of these diseases.
IMPDH1-related retinopathy (autosomal dominant): Definitive. Any retinopathy caused by a variant in the IMPDH1 gene.
Homologues: Orthologues: macaque IMPDH1 (99% identical), chimpanzee IMPDH1 (98% identical), pig IMPDH1 (92% identical), rat Impdh1 (92% identical), rabbit IMPDH1 (92% identical), dog IMPDH1 (91% identical), guinea pig IMPDH1 (86% identical), mouse Impdh1 (84% identical), tropical clawed frog impdh1 (80% identical), zebrafish impdh1a (78% identical), zebrafish impdh1b (77% identical), Drosophila melanogaster ras (59% identical), and 1 more. Paralogues in human: IMPDH2 (71% identical), GMPR (18% identical), GMPR2 (18% identical).
Diseases named in the same sentence as IMPDH1 in open-access papers:
IMPDH1 is named in the same sentence as 71 diseases in open-access papers, as found by Europe PMC text mining. Sharing a sentence is not in itself a finding about the gene and the disease. The quoted sentences say what the papers report.
retinitis pigmentosa (10 papers, 2008 to 2025). Retinitis pigmentosa (RP) is an inherited retinal dystrophy leading to progressive loss of the photoreceptors and retinal pigment epithelium and resulting in blindness usually after several decades. "IMPDH2ˋs homolog IMPDH1 (encoded by IMPDH1) exhibits predominant expression in the retina, where its pathogenic variants can result in an early‐onset progressive form of retinitis pigmentosa." (PMID 40026236, 2025). "Like IMPDH2, mutations in the gene for the other human isozyme, IMPDH1, also cause disease, in this case the retinal diseases Leber congenital amaurosis and retinitis pigmentosa." (PMID 37414152, 2023). "The clinical changes observed in the affected individual are consistent with IMPDH1 associated retinitis pigmentosa with marked macular atrophy." (PMID 34662339, 2021). "These include variants in the NAD+ or NADPH dependent retinal dehydrogenases like RDH12 that cause LCA13 and the GTP synthesis enzyme IMPDH1 that causes retinitis pigmentosa." (PMID 33107823, 2020). "Among the two IMPDH homologs that have been described in humans, IMPDH1 is linked to several types of severe retinal degeneration including retinitis pigmentosa and Leber congenital amaurosis (LCA)." (PMID 25714999, 2015). "IMPDH1 mutations cause both a dominant form of retinitis pigmentosa (RP10) and LCA11." (PMID 33107823, 2020). "Mutations in IMPDH1 also may cause a disorder known as retinitis pigmentosa-10 (RP10)." (PMID 32475352, 2020). "Interestingly, mutations in RPE65 cause retinal pigmentosa similarly to IMPDH1 mutations." (PMID 25714999, 2015). "Loss-of-function mutations in IMPDH1 (inosine monophosphate dehydrogenase 1), the rate-limiting enzyme for de novo GTP synthesis, cause retinitis pigmentosa." (PMID 37714971, 2023). "Mutations in inosine 5′-monophosphate dehydrogenase 1 (IMPDH1), a dual RNA-binding and dinucleotide-binding enzyme, cause retinitis pigmentosa, an eye disease with severe vision impairment attributable to the progressive degeneration of the photoreceptors in the retina." (PMID 26520658, 2015).
bladder cancer (6 papers, 2019 to 2025). "Moreover, novel 5-gene signature-related to lipid metabolism including IMPHD1 can also be used as independent risk factor for bladder cancer patients, suggesting that IMPDH1-targeted agents might be useful in the treatment of tumors." (PMID 36618420, 2022). "Overexpression of TWIST1 or IMPDH1/2 in 5637 cells knockdown UCA1 enhanced migration of bladder cancer cells." (PMID 37215997, 2023). "The development of IMPDH1/2 inhibitors and new theories about the regulatory roles of lncRNAs and transcription factors in the metabolic remodeling of bladder cancer cells contribute to the limitations of prospective treatment targets." (PMID 37215997, 2023). "Bladder cancer cells overexpressing UCA1 or TWIST1 had reduced migratory capacity after MPA treatment or knockdown of IMPDH1/2." (PMID 37215997, 2023). "To examine the effect of IMPDH1 and IMPDH2 on bladder cancer cell's malignant behavior, we constructed stable cell lines knockdown IMPDH1/2 in 5637 cells and UMUC2 cells." (PMID 37215997, 2023). "We studied the mechanism of IMPDH1/2 promoting the proliferation, migration, and invasion of bladder cancer cells." (PMID 37215997, 2023). "In an in vitro experiment, we demonstrated that TM4SF1, FASN, and IMPDH1 were elevated in some bladder cancer cell lines." (PMID 35480865, 2022). "For in vitro experiments, knockdown of IMPDH1 markedly inhibited cell proliferation in bladder cancer." (PMID 35480865, 2022). "IMPDH1 up-regulation has been found in many types of cancer, such as bladder cancer, brain cancer, lung cancer, ovarian cancer, and GBM42." (PMID 30796273, 2019). "Furthermore, the long non-coding RNA (lncRNA) UCA1 facilitates bladder cancer progression by recruiting the transcription factor TWIST1 to the promoter regions of IMPDH1 and IMPDH2, thereby upregulating their expression." (PMID 41179679, 2025). "We further investigated the influence of IMPDH1 on lipid metabolism-related pathways; the expressions of two key enzymes in the fatty acid synthesis pathway were measured in IMPDH1 knockdown and control bladder cancer cells." (PMID 35480865, 2022). "Based on our findings we confirmed that IMPDH1 and IMPDH2 are target genes of UCA1 controlling purine metabolism in bladder cancer." (PMID 37215997, 2023). "In other words, UCA1 affects the expression of pre-rRNA and GTPase activity by regulating IMPDH1 and IMPDH2, thus promoting the malignant behavior of bladder cancer." (PMID 37215997, 2023). "In summary, we have clarified the molecular mechanism by which UCA1 controls IMPDH1/2 expression via TWIST1 to change metabolite levels and promotes guanine nucleotide de novo anabolic reprogramming and bladder cancer progression." (PMID 37215997, 2023). "MPA and MMF inhibited the activity of IMPDH in bladder cancer cells; however, our study found that with the use of MPA and MMF, the expression of IMPDH1 and IMPDH2 proteins in bladder cancer cells increased, partially resisting the adverse effects of the decreased activity of IMPDH on tumor cells." (PMID 37215997, 2023). "Besides upregulating GPT2 expression, LncRNA UCA1 also regulates inosine monophosphate dehydrogenase 1 and 2 (IMPDH1/2) expression via TWIST1, which alters metabolite levels and promotes guanine nucleotide de novo synthesis, thereby reprogramming the metabolism of bladder cancer cells." (PMID 40384875, 2025).
Leber congenital amaurosis (6 papers, 2008 to 2023). Leber congenital amaurosis (LCA) is a retinal dystrophy defined by blindness and responses to electrophysiological stimulation (Ganzfeld electroretinogram (ERG)) below threshold, associated with severe visual impairment within the first year of life. "Deleterious mutations in IMPDH1 often cause Leber congenital amaurosis 11 (LCA11)." (PMID 32475352, 2020). "Deleterious mutations in IMPDH1 cause Leber congenital amaurosis." (PMID 32475352, 2020). "IMPDH1 not only causes adRP but also Leber congenital amaurosis (LCA)." (PMID 18552984, 2008). "Pathogenic variants in IMPDH1 are associated with autosomal dominant retinitis pigmentosa 10 (RP10), and Leber congenital amaurosis." (PMID 37569264, 2023).
autosomal dominant retinitis pigmentosa (5 papers, 2009 to 2025). Autosomal dominant retinitis pigmentosa (RP) is an autosomally dominant inherited retinal dystrophy leading to progressive loss of the photoreceptors and retinal pigment epithelium and resulting in blindness usually after several decades. "Mutations and decreased expression of the IMPDH1 gene are responsible for the disease phenotype of autosomal dominant retinitis pigmentosa." (PMID 22952885, 2012). "Furthermore, associations between genetic variants of IMPDH1 and a form of autosomal dominant retinitis pigmentosa have increased the interest in this isoform." (PMID 19635156, 2009). "It is interesting to note that causative variants in the gene inosine monophosphate dehydrogenase 1 (IMPDH1), which controls the rate-limiting step in GTP production, are also linked to autosomal dominant retinitis pigmentosa." (PMID 33584830, 2021).
lung carcinoma (5 papers, 2019 to 2024). "GDNT potentiated the role of MMF in inhibiting tumor growth and expressions of CES2 and IMPDH1/2 in lung cancer in vivo." (PMID 38419324, 2024). "We found increased MPA drug sensitivity with higher expression of IMPDH1 in lung cancer cell lines (Pearson correlation coefficient r = −0.314, p = 0.01)." (PMID 39366383, 2024). "Drug inhibition of IMPDH1 can reduce the expression of RNA polymerase I-dependent ribosomal RNA and effectively inhibit the growth of lung cancer cells in vitro." (PMID 36711025, 2023). "We also validated the association of IMPDH1 expression with OS and PFS in gastric cancer, lung cancer, liver cancer, and ovarian cancer patients using the GEO datasets through KM Plotter." (PMID 36618420, 2022). "The expression between primary lung carcinoma and its BM-paired sample (n = 23) varied (decreased, maintained, or increased) depending on the patient (paired t test p = 0.317 and 0.447, respectively, for IMPDH1 and IMPDH2)." (PMID 39366383, 2024).
clear cell renal cell carcinoma (4 papers, 2020 to 2024). "Moreover, patients with clear cell renal cell carcinoma who exhibit high IMPDH1 protein levels have shorter overall survival and disease-free survival, in which IMPDH1-assembled cytoophidia are positively associated with tumor metastasis." (PMID 39337544, 2024). "In IMPDH family, only IMPDH1 is significantly overexpressed in renal clear cell carcinoma, which is consistent with our analysis." (PMID 36618420, 2022). "High IMPDH1 expression was correlated with poorer patient survival in clear cell renal cell carcinoma." (PMID 33520699, 2020). "IMPDH1 upregulation has been reported in many types of cancer including glioblastoma, colorectal cancer, small cell lung cancers, and clear cell renal cell carcinoma." (PMID 33520699, 2020).
glioblastoma (4 papers, 2020 to 2022). The most malignant astrocytic tumor (WHO grade IV). "The results showed that high expression of H6PD, ADSSL1, ADSS, and IMPDH1 was associated with worse prognosis for glioblastoma patients." (PMID 33723244, 2021). "Increased levels of ADSL, adenylosuccinate synthase (ADSS), IMPDH1, and PPAT are associated with poor prognosis in glioblastoma patients." (PMID 34205450, 2021). "Additionally, overexpression of PPAT, IMPDH1, and ADSS correlate with worse survival among glioblastoma patients." (PMID 34205450, 2021).
glioma (4 papers, 2018 to 2025). A benign or malignant brain and spinal cord tumor that arises from glial cells (astrocytes, oligodendrocytes, ependymal cells). "Higher IMPDH1 expression is linked to poorer prognosis in renal cancer, liver cancer, urothelial cancer, glioma, and cervical cancer, while high IMPDH2 levels associate with poor prognosis in liver cancer." (PMID 40186514, 2025). "The gene expression levels of H6PD, G6PD, ADSL, APRT, GMPS, PRPS1, and IMPDH1 in human glioma patients were significantly higher than those in the control group." (PMID 33723244, 2021). "We identified 20 GSC-upregulated miRNA-targeted genes associated with significantly reduced 5-year survival in GBM patients, including previously identified glioma-promoting genes HMGA2, MYO1C, RGS4, and several novel targets, such as HPCAL1, IMPDH1, and YWHAG (orange-colored genes)." (PMID 29587824, 2018).
retinal degeneration (4 papers, 2015 to 2022). Degeneration of the retina. "For example, the mutations of inosine monophosphate dehydrogenase 1 (IMPDH1), a key enzyme in de novo nucleotide synthesis, cause severe retinal degeneration in patients, but 1-year-old Impdh1 KO mice maintain normal retinal structure." (PMID 35985423, 2022). "According to our model it might seem surprising that Impdh1-/- mice display only a slowly progressive retinal degeneration." (PMID 32254022, 2020).
retinitis pigmentosa 10 (4 papers, 2020 to 2024). Any retinitis pigmentosa in which the cause of the disease is a mutation in the IMPDH1 gene. "Variants in IMPDH1 are associated with retinitis pigmentosa type 10." (PMID 39371417, 2024). "Mutations in the IMPDH1 gene cause autosomal dominant retinal degeneration, namely retinitis pigmentosa type 10 (RP10) or Leber congenital amauriosis type 11, while mutations in the IMPDH2 gene have been only recently discovered and lead to severe juvenile neuropathies." (PMID 37512494, 2023).
Blindness (3 papers, 2020 to 2025). Blindness is the condition of lacking visual perception defined as a profound reduction in visual perception. "Dominant variants in inosine monophosphate dehydrogenase 1 (IMPDH1), a key enzyme in the de novo synthesis of purine bases, cause progressive photoreceptor death, leading to blindness." (PMID 40820815, 2025). "Taken together, our results stress the physiological relevance of GDP/GTP allosteric regulation of IMPDH1 in the maintenance of GTP homeostasis in photoreceptor cells of the retina, and highlights the disruption of this regulatory mechanism as causative of IMPDH1 associated blindness." (PMID 32254022, 2020). "Mutations in inosine monophosphate dehydrogenase 1 (IMPDH1), the enzyme responsible for the first and rate-limiting step in GTP synthesis, are associated to severe forms of inherited blindness." (PMID 32254022, 2020).
breast carcinoma (3 papers, 2012 to 2022). "Mir-19a, has been shown to target IMPDH1, decreasing the related protein expression level in breast cancer cells." (PMID 27760169, 2016). "In order to examine the effects of the IMPDH1 and NPEPL1 genes on growth suppression of breast cancer cells, the GFP expression vectors bearing the IMPDH1 or NPEPL1 gene were transfected into MCF-7 cells by electroporation." (PMID 22952885, 2012). "Among these candidate targets, IMPDH1 and NPEPL1 were identified as novel direct targets of miR-19a in the MCF-7 breast cancer cells." (PMID 22952885, 2012).
cervical cancer (3 papers, 2022 to 2025). A primary or metastatic malignant neoplasm involving the cervix. "Then we examined the expression level of IMPDH1 in four cervical cancer cell lines Hela, Caski, c33a and Siha with western blotting." (PMID 36816023, 2023). "Though the clinical specimens and experimental data showed that IMPDH1 can be a therapeutic target in cervical cancer, more detailed mechanism needs further research." (PMID 36816023, 2023). "Univariate Cox regression analysis screened 7 genes (FZR1, IMPDH1, HNRNPCL2, PCNA, GPKOW, XPA, and DDX39A) that were associated with the cervical cancer prognosis." (PMID 35909901, 2022). "It was found at single cell resolution that IMPDH1 was mainly expressed in cervical cancer cells." (PMID 36816023, 2023). "Taken together, IMPDH1 may contribute to the growth of cervical cancer and it can be a novel therapeutic target in cervical cancer." (PMID 36816023, 2023). "Compared with normal cervix tissue, the expression of IMPDH1 in cervical cancer was significantly increased, suggesting IMPDH1 may contribute to the progression of cervical cancer." (PMID 36816023, 2023). "Identification of KIN-related prognostic genes in cervical cancer revealed that a total of 5 genes (FZR1, IMPDH1, GPKOW, XPA, and DDX39A) were constructed for this risk score, and the results showed that CTLA4 expressions were negatively correlated with the risk score." (PMID 35909901, 2022). "Consistently, IMPDH1, but not IMPDH2, was found to be an indicator of poor prognosis in our cohort, suggesting that cytoophidia may be a therapeutic target in cervical cancer." (PMID 36816023, 2023).
hepatocellular carcinoma (3 papers, 2022). A malignant tumor that arises from hepatocytes. "Although high expression of IMPDH2 has been reported in various cancers, the roles of IMPDH1 in hepatocellular carcinoma (HCC) are largely unknown." (PMID 35403278, 2022).
renal carcinoma (3 papers, 2021 to 2025). A carcinoma arising from the epithelium of the renal parenchyma or the renal pelvis. "IMPDH1 has been indicated to be positively associated with renal cancer metastasis." (PMID 35480865, 2022). "Interestingly, one study demonstrated GTP-biosynthetic enzymes, including IMPDH1 and IMPDH2, were highly accumulated at the leading edge of renal carcinoma cells." (PMID 34035425, 2021).